KMO (kynurenine 3-monooxygenase)
Diseases named in the same sentence as KMO in open-access papers (continued):
Sharing a sentence is not in itself a finding about the gene and the disease.
Huntington disease (20 papers, 2008 to 2026). Huntington disease (HD) is a rare neurodegenerative disorder of the central nervous system characterized by unwanted choreatic movements, behavioral and psychiatric disturbances and dementia. "Kynurenine 3-monooxygenase (KMO) regulates the levels of neuroactive metabolites in the kynurenine pathway (KP), dysregulation of which is associated with Huntington’s disease (HD) pathogenesis." (PMID 33750843, 2021). "Dysfunction of KMO expression is associated with a broad range of neuropathologic findings, including those of Alzheimer's disease and Huntington's disease." (PMID 28446679, 2017). "KMO has recently been implicated as a therapeutic target for both Huntington’s disease and post-traumatic sepsis." (PMID 24316190, 2014). "KMO has been implicated as a therapeutic target in several disease states, including Huntington’s disease." (PMID 24316190, 2014). "For example, it has been reported that KMO activity is up-regulated in the brain region of Huntington’s disease model mice." (PMID 40630182, 2025). "Huntington’s Disease is a primary example of a neurodegenerative disorder with a pathology that correlates to the action of KMO." (PMID 38255925, 2024). "Experiments were performed both in normal animals and in R6/2 mice, an established model of Huntington’s disease (HD;), which shows microglial activation and elevated KMO activity in several brain areas." (PMID 35204197, 2022). "KMO is notable because it has been proven to be a potential therapeutic target for stroke, seizures, and Huntington's disease." (PMID 31186637, 2019). "Moreover, KMO inhibition peripherally increased kynurenic acid levels, reduced glutamate, and showed potential in preventing neurodegeneration in Alzheimer’s and Huntington’s disease mouse models." (PMID 39946208, 2025). "Studies in yeast have recognized KMO as a therapeutic target for Huntington’s disease." (PMID 39026250, 2024). "The results showed that AKT1 mainly involves 12 pathways, with the most significant being ubiquitin-mediated proteolysis; DRD4 mainly involves 7 pathways, with the most significant being AA metabolism; KMO mainly involves 4 pathways, with the most significant being Huntington disease." (PMID 39312335, 2024). "Notably, in patients with Huntington’s Disease, the central nervous system has been known to favor the KMO branch of the kynurenine pathway." (PMID 38255925, 2024). "KMO in yeast was directly related to the pathophysiology of Huntington disease by a mechanism that may involve reactive oxygen species (ROS)." (PMID 29867912, 2018). "For instance, the KMO inhibitor CHDI-340246 potently and dose-dependently modulates the KP in transgenic Huntington’s disease models, inhibiting the formation of 3-HK and QUIN while elevating neuroprotective KYNA levels in the brain." (PMID 41602107, 2026).
hepatocellular carcinoma (10 papers, 2015 to 2025). A malignant tumor that arises from hepatocytes. "KMO is a novel prognostic marker or oncogenic protein in human hepatocellular carcinoma and triple-negative breast cancer, suggesting that it is a promotor for tumour progression." (PMID 34980125, 2022). "The upregulation of KMO currently serves as an independent prognostic biomarker to identify certain liver malignancies, particularly hepatocellular carcinoma (HCC)." (PMID 35011505, 2022). "A previous study also showed that ectopic KMO expression promotes metastasis in hepatocellular carcinoma." (PMID 34683090, 2021). "Furthermore, the upregulation of the KMO gene in human hepatocellular carcinoma (HCC) and breast cancers is associated with a worse prognosis, as an elevated expression of KMO participates in the proliferation, migration, and invasion of tumors." (PMID 34683090, 2021). "In addition to participation in inflammatory processes, KMO is reported to be over-expressed in a malignant phenotype of human hepatocellular carcinoma." (PMID 37375509, 2023). "This study aimed to examine the expression of KMO inhuman hepatocellular carcinoma (HCC) and investigate the relationship between itsexpression and prognosis of HCC patients." (PMID 26099564, 2015). "For instance, kynurenine 3-monooxygenase (KMO) is significantly downregulated in hepatocellular carcinoma tissues, correlating with poor prognosis in patients with hepatocellular carcinoma." (PMID 40391162, 2025). "Immunohistochemical analysis of clinical hepatoma tissue samples revealed that COLEC10, KMO, and GNMT proteins were predominantly localized to the cytoplasm of hepatoma cells in all samples." (PMID 40026364, 2025). "In hepatocellular carcinoma (HCC) tissues, 3-HAA levels are significantly downregulated, while expression of 5-HT1D, KMO, and TDO2 is markedly upregulated." (PMID 38462620, 2024).
Alzheimer disease (8 papers, 2013 to 2023). A progressive, neurodegenerative disease characterized by loss of function and death of nerve cells in several areas of the brain leading to loss of cognitive function such as memory and language. "While none of these efforts have yet resulted in compounds investigated in the clinic due to lack of brain penetration, a non‐blood–brain barrier‐penetrating KMO inhibitor was shown to significantly improve Alzheimer’s disease symptoms and slow the disease progression." (PMID 33471408, 2021). "Nonetheless, this could be in line with a study reporting that a non‐blood–brain barrier‐penetrating KMO inhibitor has beneficial effects on both peripheral and central phenotypes in an Alzheimer’s disease mouse model." (PMID 33471408, 2021). "Recently, a very elegant study reported that inhibition of kynurenine 3-monooxygenase in peripheral organs, by increasing blood kynurenine levels and brain KYNA content, significantly reduced neurodegeneration in different transgenic models of Huntington’s and Alzheimer’s diseases." (PMID 24312407, 2013).
breast carcinoma (8 papers, 2019 to 2025). "Among all 18 analysis datasets, almost half of the datasets (8/18) suggested that KMO was overexpressed in breast cancers, which indicated that KMO was highly associated with breast cancer as compared with other types of cancers." (PMID 34683090, 2021). "In this study we disclose the association between KMO expression and the malignancy of canine mammary tumors." (PMID 31186637, 2019). "These clinical features were all consistent with the TACC3, a tumor-related gene of breast cancer, which indicates that KMO could serve as a potential diagnostic indicator in breast cancer as well." (PMID 34683090, 2021). "In a related study, KMO was found to be highly expressed in both the cytoplasm and cell membrane of clinical breast cancer cells." (PMID 41282989, 2025). "Collectively, our findings revealed that the upregulation of KMO is highly correlated with breast cancer and that KMO potentially plays an important role in the tumorigenesis of breast cancers." (PMID 34683090, 2021). "This study aimed to analyze the role of KMO in the establishment and aggressiveness of breast cancer tumors." (PMID 34683090, 2021). "Taken together, these findings highlight the tumor-promotion role of KMO in breast cancers and suggest that KMO can serve as a biomarker for prognosis prediction in breast cancer patients." (PMID 34683090, 2021). "To verify the roles of KMO in breast cancers, we validated the KMO expression in different types of breast cancers using the Oncomine analysis tool." (PMID 34683090, 2021). "A recent study demonstrated that KMO is located in the cell membranes of canine mammary gland tumors as well as in human breast cancer samples." (PMID 34440798, 2021). "Heightened levels of KMO expression were found in relatively malignant breast cancers, which ultimately resulted in a poor patient prognosis." (PMID 34683090, 2021). "KMO promotes the progression of cancers alongside its co-expressed genes and is overexpressed in patients suffering from breast cancer." (PMID 34683090, 2021). "Collectively, our data reveal the tumorigenicity of KMO and provide evidence that KMO can be an effective biomarker for further studies in human breast cancers." (PMID 34683090, 2021). "In this study, we found that the transcript-level expression of the KMO significantly increased in many types of cancers, such as breast cancers." (PMID 34683090, 2021). "Together, our findings suggest that the KMO is a tumor-related gene that participates in the tumorigenesis of breast cancer and is negatively correlated with prognosis in patients." (PMID 34683090, 2021). "KMO has been shown to have increased activity in breast cancer compared to normal cells, specifically being upregulated on the protein level in the HER2+ subtype and having elevated transcription levels in the Triple Negative subtype." (PMID 32620123, 2020). "KMO has been previously shown to promote breast cancer progression in triple negative breast cancer while being highly upregulated in HER2+ breast cancer." (PMID 32620123, 2020). "Our results also showed that KMO plays a role in controlling cell growth and malignancy in canine mammary tumors." (PMID 31186637, 2019). "A high level of KMO is correlated to the malignancy of breast cancers, leading to a poor prognosis in patients, which indicates that KMO could be a hub regulator and/or biomarker in breast cancers." (PMID 34683090, 2021). "In addition, KMO expression was positively correlated with the malignant clinical features of patients with breast cancer, such as TNBC and a nodal-positive status, along with patients with a higher Nottingham prognostic index (NPI)." (PMID 34683090, 2021). "KMO was significantly upregulated in eight types of cancers, and especially in breast cancers." (PMID 34683090, 2021). "Notably, an elevated KMO is positively correlated with “relatively malignant” breast cancers, including with TNBC, node-positive, and patients with a high grade of NPI." (PMID 34683090, 2021).
breast carcinoma (continued). "First, the upregulation of KMO can suppress the antitumor immune responses in patients with breast cancers, and second, with an elevated KMO expression, the activation of the kynurenine pathway, via STAT3 and pSTAT3, potentially promotes the development of tumors into more aggressive phenotypes." (PMID 34683090, 2021). "Second, a large number of clinical samples, such as patient IHC stains, would be needed to support these findings, and although further evidence is needed, our data do suggest that KMO plays a vital role in human breast cancers by facilitating the proliferation, invasion, and metastasis of tumors." (PMID 34683090, 2021). "Decreasedformation of these Kyn metabolites by KMO inhibition can also preventtumoral immune escape and it is noteworthy that KMO is upregulated inhepatocellular carcinoma andtriple negative breast cancer.The potential impact of KMO inhibition on XA formation remains to beexplored." (PMID 31105983, 2019). "In addition, the migration and invasion of MDA-MB-231 cells were significantly reduced after blocking KMO, suggesting that KMO may promote the growth and metastasis of breast cancer cells." (PMID 41282989, 2025). "Moreover, a high KMO expression in breast cancers led to a worsening prognosis." (PMID 34683090, 2021). "However, it remains unclear whether the role of the KMO contributes to tumorigenesis and immune functions in human breast cancer." (PMID 34683090, 2021). "Our previous studies reported that kynurenine 3-monooxygenase (KMO) can affect cancer-stemness and is overexpressed in several TNBC cells, which indicates that KMO plays a vital role in breast cancers." (PMID 34683090, 2021). "Kynurenine 3-monooxygenase (KMO) is overexpressed in several tumors and participates in the progression of breast cancer tumorigenesis, including cancer types such as triple-negative breast cancer (TNBC)." (PMID 34683090, 2021). "Furthermore, the top ten KMO-correlated genes were the chemokines and pro-inflammatory cytokines known to be involved in the progression of various cancers, therefore, KMO may facilitate breast cancers via synergistically regulating inflammatory responses in tumors with these hub genes." (PMID 34683090, 2021). "Taken together, although the detailed mechanisms still need to be fully elucidated, our results have offered significant evidences of involvement of KMO in CMT progression and provided precious advice for further study on human breast cancer therapy." (PMID 31186637, 2019). "KMO and KYNU inhibitors may therefore be considered as potential options for the treatment of breast cancer and cutaneous squamous cell carcinoma." (PMID 34201791, 2021). "This study aimed to verify whether KMO is a potential biomarker for the diagnosis of CMT and whether KMO can be a useful molecule in prognostic prediction and therapeutic development for mammary tumors in the future." (PMID 31186637, 2019). "Therefore, we further compared the levels of KMO mRNA expression in breast cancers (n = 1085) with those in normal breast tissues (n = 291) using the GEPIA database, and the results also showed that KMO was overexpressed in breast cancers." (PMID 34683090, 2021).
colorectal cancer (7 papers, 2021 to 2022). A primary or metastatic malignant neoplasm that affects the colon or rectum. "KMO is overexpressed in colorectal cancer patients, and high KMO expression predicts a higher risk of metastasis and decreases survival rate." (PMID 35681770, 2022). "A recent study investigated the correlation between upregulated KMO activity and poor clinical outcomes in colorectal cancer (CRC) patients and demonstrated that KMO inhibition suppressed CRC cell proliferation in vitro." (PMID 34680327, 2021). "Furthermore, the expression of KMO on GBM and other solid tumors such as melanoma, mammary, and colorectal cancer has been recently reported, pointing to KMO as a promissory subject of study." (PMID 36355137, 2022). "However, KMO overexpression is related to malignancy and poor prognosis in patients with triple-negative breast cancer and colorectal cancer." (PMID 34440798, 2021). "Additionally, inhibition of KMO activity represses colorectal cancer cell migration, invasion, and tumor sphere formation." (PMID 34440798, 2021). "Elevated KMO levels also led to a poor prognosis in patients with TNBC, colorectal cancer, and HCC." (PMID 34683090, 2021).
triple-negative breast carcinoma (7 papers, 2020 to 2022). An invasive breast carcinoma which is negative for expression of estrogen receptor (ER), progesterone receptor (PR), and human epidermal growth factor receptor 2 (HER2). "KMO is also amplified in 5 to 30% of breast cancers and promotes triple-negative breast cancer progression." (PMID 35681770, 2022). "Recent studies showed that KMO has a prognostic value on triple negative breast cancer, mainly on the recurrence and metastasis." (PMID 36355137, 2022). "KMO was also shown to enhance triple-negative breast cancer cell proliferation and migration." (PMID 35681770, 2022). "Furthermore, some authors observed that the expression levels of KMO and KYNU are potently upregulated in the course of HER2-enriched and triple-negative breast cancer subtypes, as well as cutaneous squamous cell carcinoma." (PMID 34201791, 2021).
acute pancreatitis (6 papers, 2016 to 2025). An acute inflammatory process that leads to necrosis of the pancreatic parenchyma. "This dual action makes KMO a vital therapeutictarget in conditions such as neurodegenerative diseases, psychiatricdisorders, acute pancreatitis, and immune dysregulation." (PMID 40949262, 2025). "Inhibition of kynurenine 3-monooxygenase (KMO) protects against multiple organ dysfunction (MODS) in experimental acute pancreatitis (AP)." (PMID 27669975, 2016). "Therefore, the activation of KMO leads to an increase in kynurenine levels, which are critical for the development of post‐traumatic sepsis, and an increase in kynurenine and 3‐HK levels is related to the development of organ failure in acute pancreatitis (Abdel‐Magid, 2015)." (PMID 32148781, 2020). "Kynurenine-3-monooxygenase (KMO) is an emerging clinical target for treatment of neurodegenerative diseases and acute pancreatitis." (PMID 28604669, 2017).
diabetes (6 papers, 2017 to 2026). "Attenuation of the consequences of peripheral KMO deficiency might be a new target for prevention/treatment of obesity and diabetes in SP." (PMID 28748226, 2017). "A decline in KAT activity correlates with cataract severity, while upregulation of KMO is prominent in diabetes and glaucoma, revealing disease-specific metabolic dysregulation." (PMID 40648903, 2025). "FBG levels were higher in KMO KO mice relative to WT mice, suggesting that the mice had developed mild diabetes or that they were in a prediabetic state." (PMID 32151061, 2020). "Additionally, therapeutic strategies targeting this pathway—such as KMO inhibitors, KYNA analogs, or antioxidant adjuvants—warrant exploration for their potential to mitigate diabetes-associated ocular disease." (PMID 40648903, 2025). "Oxenkrug, van der Hart, Roeser, and Summergrad (2017) found that inhibition of peripheral KMO may be a new measure for the prevention of obesity and diabetes, and KMO expression in the adipose tissue was positively correlated with increased HbAlc level." (PMID 32148781, 2020). "As KMO knockout mice showed foot process effacement and proteinuria, the kynurenine pathway might have an important role in kidney disease progression of patients with diabetes." (PMID 33974145, 2021). "In systemic disease, diabetes mellitus hyperactivates indoleamine 2,3-dioxygenase (IDO) and downstream KP enzymes, driving KMO flux and oxidative stress in both lens and retinal tissues." (PMID 40648903, 2025). "It should be noted, however, that the absence of KMO resulted in only mild elevation of blood glucose (193 ± 10 in KMO KO and 231 ± 36 in STZ-induced diabetes in 2 weeks)." (PMID 32151061, 2020). "None of the co-morbid pathologies of diabetes (reduced body weight, reduced glucose tolerance, and reduced insulin sensitivity) were present in the KMO KO mice." (PMID 32151061, 2020). "When comparing patients with and without diabetes, we found that KMO activity was increased more in diabetic patients (median = 0.765, IQR = 0.498–1.095) than in non-diabetic patients (median = 0.545, IQR = 0.364–0.802); this was supported by a Mann–Whitney U test (U = 820, p = 0.039, r = 0.257)." (PMID 40648903, 2025).